MUC1 (mucin 1, cell surface associated)
Diseases named in the same sentence as MUC1 in open-access papers (continued):
Sharing a sentence is not in itself a finding about the gene and the disease.
cancer (continued). "Interestingly, a recent paper has shown a significant correlation between ‘cancer-associated MUC1’ (a mixture of glycophenotypes) and macrophages when staining with CD16346." (PMID 33149188, 2020). "Beyond global targeting of MUC1 or MUC1 tumour-associated antigen, targeting MUC1-CT and its nuclear translocation might represent a promising option for the treatment of several types of cancer, as well as IPF." (PMID 31514468, 2019). "Expression of MUC1 mucin was considered to occur strictly within epithelial cells until our original studies demonstrated that soluble cancer-associated MUC1 mucin can inhibit T cell responses and that activated human T cells also synthesize and express MUC1 mucin on their surfaces." (PMID 31468283, 2019). "More recently, cancer-associated Tn glycoform of MUC1, a neoantigen expressed on the cell surface in a variety of cancers, has also been targeted to engineered CAR-T cells and have been shown to be successful in controlling tumor growth in xenograft models of T-cell leukemia and pancreatic cancer." (PMID 29448937, 2018). "In addition, MUC1 expression is associated with resistance to anti-cancer drugs, presumably leading poor patient prognosis." (PMID 29987260, 2018). "CA15-3 (MUC1) is yet another biomarker, which has been extensively implicated in a variety of cancers, and is routinely used as a prognostic indicator, and a measure of cancer severity." (PMID 28677660, 2017). "Furthermore, we report that only a few cancer subtypes carry MUC1 mutations, where extracellular region point mutation T112P was commonly seen and responsible for 50% of the MUC1 mutations observed in PDAC." (PMID 28978023, 2017). "Finally, diagnostic sensitivity for stage I and II carcinomas was significantly higher in serum WFA-sialylated MUC1 than in CA19-9 and CEA." (PMID 27358229, 2017). "MUC1 is abnormally overexpressed in numerous carcinomas and associated with poor prognosis." (PMID 28796259, 2017). "Additionally, the epigenetic control of MUC1 in cancer cells has been associated with H3K9 modification and DNA methylation." (PMID 26930718, 2016). "Underglycosylated forms of MUC1 are highly expressed in breast, colon, pancreas, and bladder tumors, among others, but not in normal tissues, and are often associated with epithelial to mesenchymal transition and invasiveness of cancer cells." (PMID 27754373, 2016). "The cancer-associated MUC1 with aberrant glycosation is highly immunogenic." (PMID 27825118, 2016). "Cell surface-associated mucin 1 (MUC1) (previously known as PUM, MCKD1), a highly glycosylated transmembrane heterodimeric protein and a transmembrane member of the mucin family, is highly expressed in various human malignant tumors including prostate cancers and is correlated with a poor prognosis." (PMID 25971429, 2015). "Stratified analyses of the MUC1 rs4072037 polymorphism on cancer risk." (PMID 24755768, 2014). "In many cancers MUC1 and IL-8 are overexpressed and are associated with poor prognosis." (PMID 24932473, 2014). "Therefore, we have extensively reviewed the literature and performed a meta-analysis based on all eligible published case-control studies to evaluate the association between MUC1 rs4072037 polymorphism and cancer susceptibility." (PMID 24755768, 2014). "Mucin 1 (MUC1) is a tumor associated glycoprotein that plays a role in cancer progression." (PMID 24932473, 2014). "Recognition of cell-bound MUC1-TM-associated SP could also result from improper function of the cancer-associated, ER–associated SPase." (PMID 24416403, 2014). "However, further well-designed studies in large cohort of different ethnic origins and cancer types are needed before the application of MUC1 rs4072037 polymorphism as cancer biomarker in clinical settings." (PMID 24755768, 2014). "Most notably, overexpression of Muc1 has been shown to be associated with several types of cancers." (PMID 23977093, 2013).
cancer (continued). "Furthermore, the presence of natural abs to MUC1 in healthy individuals and their relatively low incidence in patients with cancer will lead to diagnostic markers with a low specificity and sensitivity." (PMID 24212946, 2011). "In addition to gene overexpression, genetic variations in MUC1 have also been reported as risk factors contributing to cell mobility and the severity of cancer." (PMID 21349170, 2011). "Mucin 1 (MUC1) is a glycoprotein that was first identified as a tumour-associated antigen in the mid-1980s; it is overexpressed and aberrantly glycosylated in many carcinomas including NSCLC." (PMID 21982342, 2011). "Like the MAPK pathway, AKT signaling has been linked to MUC1 in cancer." (PMID 16846534, 2006). "The MUC1 oncogene has been linked to apoptosis, proliferation, and transcription in cancer." (PMID 16846534, 2006). "Adenocarcinomas from these organs frequently overexpress and aberrantly glycosylate MUC1 leading to the suggestion that loss of MUC1 topological restriction and increased cellular expression in cancer cells may contribute to the malignant phenotype." (PMID 12966437, 2003). "Finally, we were interested to see whether changed expression of MUC1 in lymph node metastases associated with distant spread of carcinoma or worse outcomes." (PMID 41332218, 2025). "Hypothesizing that the major difference between the outcome of the vaccine in preclinical models and clinical trials is the high level of immune suppression in cancer patients, we began to develop models and MUC1 vaccines for cancer prevention in patients at risk; before immune suppression develops." (PMID 39450169, 2024). "Since the gene localization of MUC1 is well defined, altering its expression in early cancers through gene regulation methods could potentially impact cell adhesion and polarity, thereby reducing the risk of cancer metastasis." (PMID 39491020, 2024). "Therefore, MUC1 might be utilized in clinical settings as a diagnostic marker for cancer development and recurrence and might be even used as a therapeutic target." (PMID 38540735, 2024). "MUC-1 is a highly glycosylated protein encoded by the mucin 1 gene that has been established for diagnostic applications, which is over-expressed in the most malignant epithelial cell surface; further, it has been chosen for early detection and treatment of cancers." (PMID 36615606, 2023). "In addition to the ADC approach, another potential strategy is to exploit the cancer-specific glycoform of MUC21 for engineered immune cell therapies, such as CAR-T cell therapy targeting the cancer associated Tn (GalNAca1-O-Ser/Thr)-glycoform of MUC1 to control various adenocarcinomas." (PMID 37858248, 2023). "Interestingly, MUC1-induced mitophagy is associated with increased oncogenicity of cancer cells." (PMID 36289190, 2022). "Additionally, ga-tipotuzumab (PankoMab) specifically reacts with cancer-associated MUC1." (PMID 34070311, 2021). "Besides, MUC1 induces the expression of PDGF-A in cancer cells in association with HIF-1α." (PMID 33836774, 2021). "The majority of such growth factor receptors would be expressed basally and would normally be separated from MUC1 by epithelial tight junctions, so that they would only be able to associate following damage to epithelial integrity or a loss of apical–basal polarity as is seen in cancer cells." (PMID 32194962, 2020). "Furthermore, it has been widely demonstrated that cancer gives rise to distinctive, aberrant MUC1-associated glycosylation, likely due to mutations in the Cosmc chaperone for T-synthase (core 1 β3-galactosyltransferase), increased sialylation and/or deregulation of glycosyltransferase genes." (PMID 26788922, 2016). "Although the levels of mt-associated MUC1 C-ter are linked to the intrinsic Δψm of cancer cells and MUC1 C-ter has been reported to integrate into the outer mitochondrial membrane, it is unclear whether mitochondrial MUC1 C-ter contributes to regulation or maintenance of the Δψm." (PMID 21966455, 2011).
cancer (continued). "Therefore, the MUC1-Associated Proliferation Signature (MAPS) described in the current report not only serves as a new classifier, but also sheds light on the mechanisms of MUC1-CD-associated tumorigenesis and suggests potential gene products and drugs for targeted cancer therapy." (PMID 20459602, 2010). "MUC1 inhibitor GO-203 and anti-TA-MUC1 therapeutic antibody also were used within different cancer cells." (PMID 41516394, 2026). "The results show that the levels of these proteins were able to be induced by sEVs from these cancer cells, along with an enhanced level of MUC1 protein in treated HUVEC cells." (PMID 41516394, 2026). "MUC1 is a transmembrane glycoprotein commonly over-expressed and aberrantly glycosylated in many cancers, particularly in PDAC." (PMID 41596231, 2026). "MUC1 depletion significantly reduced glucose consumption and lactate production and increased the resistance of cancer cells to sunitinib administration." (PMID 41533164, 2026). "In one study, Lactococcus lactis was engineered to express the tumor antigen mucin 1 (MUC1), a glycoprotein overexpressed in various cancers, including breast and ovarian cancers." (PMID 41355950, 2026). "In comparison with both of the controls (CTL and Isotype IgG treated), the levels of cholesterol uptake were significantly reduced by the anti-MUC1 antibody within three cancer cell lines and less reduced in normal HUVEC cells." (PMID 41516394, 2026). "The vaccination resulted in a significant reduction in tumor size in mouse models of MUC1-expressing cancers, demonstrating the potential of engineered probiotics as live bacterial vaccines for cancer immunotherapy." (PMID 41355950, 2026). "The prognostic role of MUC1 alterations in terms of overall survival (OS), cancer specific survival (CSS), and progression-free survival (PFS) were estimated using the Kaplan-Meier method." (PMID 41533164, 2026). "As an oncoprotein that forms the cytoplasmic part of the MUC1 transmembrane protein, MUC1-C is overexpressed in many human cancers." (PMID 41516394, 2026). "In cancer cells, MUC1 induces metabolic reprogramming, modulates the immunoflogosis, and promotes metastatic progression." (PMID 41533164, 2026). "Notable downregulated genes included Mki67, Ccn1, Muc1, Atf3, Ntrk2, Arid5b, Igf1r, Igf2bp2, Cd47, and Cd37 (oncogenic function) and integrin-related genes, Itga7, Itga11, Itgam and Notch1 (cancer stem cell markers)." (PMID 39946195, 2025). "Its altered expression in various cancers, including breast, ovarian, and lung cancers, makes MUC-1 a significant biomarker for cancer diagnosis and prognosis." (PMID 40236691, 2025). "Carcinoembryonic antigen and mucin 1 (MUC1) are cancer antigens that are known to be expressed by the malignancies for which patients with LS are at risk." (PMID 41463230, 2025). "In cancer cells, clathrin-mediated endocytosis increases intracellular intake MUC1 due to its hypoglycosylation." (PMID 40001578, 2025). "This selective targeting highlights the potential of MUC1-directed CAR-T therapy as a promising treatment option for cancers, such as HNSCC, with reduced off-target toxicity." (PMID 40312353, 2025). "Subsequently, GUCA2A was identified as a potential target for gain of function studies, leading to its amplification and cloning into gene constructs featuring both a robust CMV promoter and a cancer-specific MUC1 promoter." (PMID 41960141, 2025). "BI1361849 is an RNA-based cancer vaccine composed of six mRNAs including MUC1, survivin, NY-ESO-1, 5T4, MAGE-C2, and MAGE-C1." (PMID 40006675, 2025).
cancer (continued). "Numerous reports have demonstrated that the interactions of Gal-3 with MUC1 via T antigen are essential for metastatic cell adhesion in cancer progression." (PMID 41154387, 2025). "One such candidate is MUC1, a transmembrane glycoprotein, which is overexpressed and specifically glycosylated in many cancers." (PMID 41154387, 2025). "In both cancer types, we observed significant methylation differences in regions around cancer-related genes, such as MUC1 and HSPA1A,37,58 in which it is difficult to detect methylation status with short-read sequencing." (PMID 41187747, 2025). "For example, inhibiting O-glycosylation of MUC1 or MUC5AC sensitizes cancer cells to chemotherapy and radiotherapy." (PMID 40655139, 2025). "The significance of Muc1, Muc4, and Muc5AC has been highlighted in the progression of cancer using a KrasG12D;Pdx1-Cre murine model." (PMID 40699746, 2025). "This mechanistic insight explains how MUC15, despite being a relatively small glycoprotein compared to mucins like MUC1, can significantly influence cancer cell behavior through size‐dependent physical interactions at the cell‐matrix interface." (PMID 41082352, 2025). "Cytoplasmic MUC1 positivity in cribriform structures was associated with BRAF mutation and with serrated cancer type." (PMID 41332218, 2025). "MUC1 modulates the transcription of cell adhesion molecules and signaling pathways, promoting cancer cell migration, invasion, and immune evasion." (PMID 40699805, 2025). "Aberrant expression of MUC1 has been found in several types of cancer, including gastric, breast, ovarian, and bladder cancers." (PMID 41012179, 2025). "MUC1 has been shown to play a pivotal role in inducing prostaglandin and growth factor synthesis, which are crucial for promoting cancer cell proliferation and survival." (PMID 40655139, 2025). "The impairment of MUC1-desmosomal interaction reverses anoikis resistance, also impairing cancer cell ability to form colonies and adhere to the ECM and/or neighboring cells." (PMID 40001578, 2025). "Owing to its expression in many cancer types, various treatments targeting Tn‐MUC1, including chimeric antigen receptor‐T cells (CAR‐T) and vaccines, have been developed." (PMID 40844495, 2025). "The clinical implications of MUC1 are significant, as it serves as a tool for the detection and prognosis of cancers, particularly epithelial adenocarcinomas found in organs, such as the lungs, liver, colon, breast, pancreas, and ovaries." (PMID 40699746, 2025). "MUC1 has been identified as a promising therapeutic target and a clinically relevant biomarker in cancer treatment." (PMID 41041313, 2025). "In disease states, MUC1’s role shifts toward facilitating cancer cell growth, metastasis, and invasion, while simultaneously diminishing the responsiveness of cancer cells to chemotherapy and radiotherapy." (PMID 40655139, 2025). "Due to its overexpression, specifically altered glycosylation, and participating in different steps of GC development, MUC1 is considered an attractive target in cancer treatment." (PMID 41154387, 2025). "MUC1 is the second-best potential TAA for creating cancer vaccines, according to the National Cancer Institute." (PMID 40625850, 2025). "In diseased tissues, particularly cancer, can lead to alterations in MUC1 expression and structure, manifesting as overexpression and formation of a dense membrane layer." (PMID 40655139, 2025). "Mesenchymal stem cell-derived exosomes encapsulated Dox and were functionalized with MUC1 aptamers for targeted delivery to MUC1-positive cancer cells." (PMID 40530018, 2025). "Due to MUC1’s aberrant expression in cancer epithelial cells, MUC1 recently raised scientific interest as a potential prognostic and/or therapeutic biomarker." (PMID 40001578, 2025). "MUC1 was observed to function as a pro-inflammatory factor in different cancers, including pancreatic, breast, and colorectal, utilizing the leukocyte adhesion pathway." (PMID 40649198, 2025).
cancer (continued). "Within cancer cells, MUC1 impacts signaling pathways and controls gene expression both during transcription and after transcription." (PMID 40699746, 2025). "Two of these (cancer cells and LEC1, cancer cells and LEC2) exhibited high expression of cancer cell-associated genes such as KRT19, CDH1, MUC1, and TFF1, suggesting their close interaction with cancer cells." (PMID 41249124, 2025). "While MUC1 is typically present on the apical surface of epithelial cells, it is often overexpressed in cancer cells, with levels up to 100 times higher than those found in normal cells." (PMID 40333213, 2025). "Truncation of glycan on the mucin 1 (MUC1) protein found on the membrane of almost all human cells is one of the major hallmarks in cancer progression." (PMID 40266147, 2025). "Mucin-1 (MUC1) is a glycoprotein that is aberrantly glycosylated and overexpressed in many cancers, including TNBC." (PMID 40626008, 2025). "Mucins, specifically MUC1, are overexpressed in cancer, and MUC1 expresses aberrantly glycosylated TA epitopes in 80% of PDAC patients." (PMID 40358156, 2025). "The common genes that exhibited concordant expression trends in CRC and PDAC KRAS‐mutant cells compared with their corresponding KRAS‐WT cancer cell lines were MUC1, ITGA3, and PHLDA." (PMID 40013338, 2025). "Despite being mostly considered an oncogene, overexpressed in multiple solid tumors, MUC1 is also involved in metabolic reprograming of cancer cells, contributing to pancreatic cancer radioresistance." (PMID 40610411, 2025). "The glycocalyx, composed of dense glycoproteins such as MUC1, is markedly expanded in cancers, where it impedes immune cell access and antigen engagement, thereby reducing efficacy." (PMID 41372740, 2025). "As the stage of cancer increased, MUC1-positive expression increased significantly, with the highest MUC1 expression observed in Stage IV BrCa tissue (93.9%) compared to Stage III (36.5%), Stage II (11.3%), and Stage I (0.4%)." (PMID 41471303, 2025). "The study highlighted the need for further research into MUC1′s role in maintaining cancer stem cell characteristics and its detailed mechanisms of action to develop more effective treatments for PC." (PMID 40699746, 2025). "Aside from cancer progression, MUC1 is also involved in chemoresistance in PC cells through the inhibition of BRCA1 to enhance glucose utilization." (PMID 40699805, 2025). "MUC1-C, the C-terminal domain of MUC1, functions as an oncoprotein, promoting the upregulation of genes and proteins involved in signaling pathways that are dysregulated in advanced cancers." (PMID 40699805, 2025). "Research has demonstrated that the production of antibodies against MUC1 and the activation of cellular immune responses can positively influence cancer patient outcomes." (PMID 40333213, 2025). "MUC1 is often overexpressed and abnormally glycosylated in many cancers, including breast, pancreatic, and lung cancer." (PMID 39796763, 2025). "The dominant antigens on cancer cells were EpCAM, MUC-1, TTF-1, Ki67, cytokeratin, and CD56, whose average expression was around 70–60%." (PMID 39941799, 2025). "Here, we demonstrate that MUC1 promotes symmetric division and expansion of cancer stem‐like cells (CSLCs) in SCLC." (PMID 40349179, 2025). "In another study, a tapered SMF with a 50 μm waist diameter and a 0.7 m taper length was prepared via a flame-based heat-and-pull procedure, then coated with PDMS combustion products and GO to detect the cancer biomarker MUC1." (PMID 40942658, 2025). "Examples of MUC1-based cancer vaccines include subunit vaccines, DNA vaccines, viral vector vaccines, dendritic cell vaccines, and glycoprotein vaccines." (PMID 40699805, 2025). "Disease progression and treatment relapse are attributed to MM cancer stem cells (CSCs) and signaling molecules such as MUC1 and XBP1." (PMID 40179083, 2025).